ATG9B (autophagy related 9B)
Description:
Phospholipid scramblase involved in autophagy by mediating autophagosomal membrane expansion. Cycles between the preautophagosomal structure/phagophore assembly site (PAS) and the cytoplasmic vesicle pool and supplies membrane for the growing autophagosome. Lipid scramblase activity plays a key role in preautophagosomal structure/phagophore assembly by distributing the phospholipids that arrive through ATG2 (ATG2A or ATG2B) from the cytoplasmic to the luminal leaflet of the bilayer, thereby driving autophagosomal membrane expansion (By similarity). In addition to autophagy, also plays a role in necrotic cell death (By similarity).
Synonyms: APG9L2; NOS3AS; FLJ14885; SONE
Tractability: Antibody: UniProt predicts a signal peptide or a membrane-spanning region. PROTAC: ubiquitination databases record sites on it.
Gene: Protein-coding gene on chromosome 7 (151,012,209 to 151,024,499, reverse strand). Ensembl gene ENSG00000181652.
Subcellular location: Preautophagosomal structure membrane
Pathways (Reactome):
Autophagy: Macroautophagy
Gene Ontology:
Molecular function: phospholipid scramblase activity
Biological process: autophagosome assembly; bone morphogenesis; mitophagy; piecemeal microautophagy of the nucleus; programmed necrotic cell death; protein localization to phagophore assembly site; reticulophagy; autophagy; plasma membrane phospholipid scrambling
Cellular component: phagophore assembly site membrane; autophagosome; endoplasmic reticulum membrane; Golgi membrane; phagophore assembly site; recycling endosome membrane; trans-Golgi network; cytoplasm
Genetic constraint (gnomAD): Loss-of-function variants: 92 observed, 78.23 expected, observed/expected ratio (o/e) 1.18, 90% interval 0.99 to 1.4. The synonymous counts are far from expectation, so gnomAD's model fits this gene poorly and the ratio says little. Missense variants: 1,344 observed, 1,080.6 expected, observed/expected ratio (o/e) 1.24, 90% interval 1.19 to 1.3. Synonymous variants: 599 observed, 471.99 expected, observed/expected ratio (o/e) 1.27, 90% interval 1.19 to 1.36.
Homologues: Orthologues: chimpanzee ATG9B (99% identical), macaque ATG9B (97% identical), rabbit ATG9B (90% identical), dog ATG9B (87% identical), rat Atg9b (87% identical), mouse Atg9b (87% identical), pig ATG9B (86% identical), guinea pig ATG9B (75% identical), tropical clawed frog atg9b (41% identical), zebrafish atg9b (41% identical), Drosophila melanogaster Atg9 (30% identical), Caenorhabditis elegans atg-9 (27% identical). Paralogues in human: ATG9A (40% identical).
Diseases named in the same sentence as ATG9B in open-access papers:
ATG9B is named in the same sentence as 31 diseases in open-access papers, as found by Europe PMC text mining. Sharing a sentence is not in itself a finding about the gene and the disease. The quoted sentences say what the papers report.
colorectal cancer (6 papers, 2020 to 2024). A primary or metastatic malignant neoplasm that affects the colon or rectum. "In gastric and colorectal cancers, ATG9B has frameshift mutations, suggesting that these mutations may affect cancer progression by regulating autophagy." (PMID 37616056, 2023). "Additionally, proteins such as ATG9B facilitate colorectal cancer spreads by promoting the formation of focal adhesions." (PMID 39678496, 2024). "It has been postulated that the deregulation of ATG9B may contribute to promotion of the development of stomach and colorectal cancers." (PMID 32993062, 2020).
breast carcinoma (5 papers, 2017 to 2025). "Recent studies reported that ATG9B is highly expressed in some cancer, including cervical cancer and renal clear cell carcinoma, while it is lower expressed in hepatocellular carcinoma and breast cancer." (PMID 34131310, 2021). "We here concluded that autophagy induced by SAHA in breast cancer cells is involved in TRAIL DR5, and this induction may be related to the increased catalytic activity of ATG4B (or other ATG molecules with similar functions, such as ATG9B)." (PMID 29018571, 2017). "However, in breast cancer, study showed that downregulation of ATG9B but not its orthologue ATG9A could accelerate breast cancer progression, signifying that ATG9A and ATG9B have different biological function in cancer." (PMID 34131310, 2021).
cervical cancer (5 papers, 2016 to 2023). A primary or metastatic malignant neoplasm involving the cervix. "In addition, down-regulation of HPV 16E6/E7 (16E6/E7) can inhibit the expression of autophagy gene ATG9B, thereby inhibiting cell proliferation and promoting early cervical cancer cell apoptosis." (PMID 37616056, 2023). "It is worth noting that HS-27a and HS-5 were obtained from primary hMSCs transformed with Human papillomavirus 16E6/E7, which activates autophagy via Atg9B and LAMP1 in cervical cancer cells." (PMID 32484831, 2020). "Our results suggest that Atg9B and LAMP1, as candidate downstream regulators of 16E6 and 16E7, play a positive role in promoting autophagy flux, as 16E6 and 16E7 do, in cervical cancer cells." (PMID 31215164, 2019). "Our results suggest that Atg9B and LAMP1 overexpressions compensate, at least partially, the autophagic blockage induced by 16E6E7 knockdown in cervical cancer cells." (PMID 31215164, 2019). "Our findings verified that 16E6/E7 activated autophagy via accelerating autophagosome formation and degradation, and Atg9B and LAMP1 were involved in the process of 16E6/E7 modulating autophagy, suggesting that targeting autophagy may be a potential approach in cervical cancer therapeutics." (PMID 31215164, 2019).
clear cell renal cell carcinoma (5 papers, 2021 to 2024). "Studies have reported that ATG9B was overexpressed in clear-cell renal cell carcinoma but down-regulated in hepatocellular carcinoma and was associated with the cancer prognosis." (PMID 34809598, 2021). "ATG9B expression significantly correlates with TNM staging, distant metastasis, and survival time of clear cell renal cell carcinoma patients." (PMID 33679977, 2021).
glioma (5 papers, 2019 to 2025). A benign or malignant brain and spinal cord tumor that arises from glial cells (astrocytes, oligodendrocytes, ependymal cells). "A higher level of ATG9B expression was associated with GBM compared to low-grade glioma." (PMID 32943609, 2020). "Further analysis revealed that mIDH1 cells express significantly higher levels of ATG9b protein in both mouse and human mIDH1 glioma cells." (PMID 40964044, 2025). "ATG9B, which was vital in phagophore formation, was appraised as a potential core gene for autophagy in maintaining the stemness of gliomas." (PMID 35882624, 2022). "With in vitro and in vivo data, we demonstrate that knockdown of ATG9B reduces the stemness properties of glioma." (PMID 35882624, 2022). "By analyzing markers of autophagy and autophagosomes, we found that knockdown of ATG9B in ASCL2‐overexpressing glioma cells significantly blocked ASCL2‐mediated upregulation of autophagy." (PMID 35882624, 2022). "The promoter of ATG9B (2 kb upstream of the transcriptional start site) was inserted into the dual‐luciferase reporter plasmid, and glioma cells with ASCL2 overexpression exhibited higher transcriptional activity than those with Ctrl overexpression." (PMID 35882624, 2022). "Silencing of ATG9b in mIDH1 human glioma cells and mIDH1 mouse NS models significantly reduced cell viability when combined with IR, compared to siRNA treatment alone (SJ-GBM2 mIDH1: P < 0.0001; CPAI mIDH1 mouse NS: P < 0.0001; RPAI mIDH1 NS: P < 0.0001; NPAI mIDH1 NS: P< 0.0001)." (PMID 40964044, 2025). "These in vitro data implied that silencing ATG9B reduced the stemness of glioma." (PMID 35882624, 2022). "Furthermore, we measured ATG9B expression in 338 glioma samples from our hospital (SW cohort) with IHC and downloaded the mRNA expression of ATG9B in gliomas (TCGA cohort) in the TCGA LGGGBM dataset." (PMID 35882624, 2022). "ATG9B expression increased in glioma samples according to the WHO grade." (PMID 35882624, 2022). "As ATG9B was elevated in gliomas, we investigated the function of ATG9B in maintaining stemness." (PMID 35882624, 2022). "An ATG9B probe was developed to confirm the status of ATG9B in glioma samples." (PMID 35882624, 2022). "We first studied the correlation of ATG9B expression with glioma stemness markers." (PMID 35882624, 2022). "We constructed overexpression plasmids to transfect glioma cells, and only elevated ASCL2 could significantly increase the mRNA and protein expression of ATG9B, which was consistent in multiple glioma cells transfected with an ASCL2 overexpression lentivirus." (PMID 35882624, 2022). "To demonstrate this hypothesis, we first analyzed the expression of core autophagy genes in glioma cells overexpressing ASCL2 relative to control cells, and ATG9B was significantly elevated in two glioma cell lines." (PMID 35882624, 2022). "In two gliomas datasets, ATG9B was significantly correlated with multiple glioma stemness markers." (PMID 35882624, 2022). "We investigated whether ATG9B gain or high expression was correlated with poor overall survival of glioma patients." (PMID 35882624, 2022). "However, through TCGA database analysis, we found significant increases of ATG9B in GBM tissues when compared to low-grade glioma (grade II), suggesting the clinical relevance of ATG9B in GBM." (PMID 32943609, 2020). "Furthermore, inhibition of ATG9B also impeded ASCL2‐mediated elevation of colony formation and self‐renewal abilities, which implied that in addition to autophagy, ASCL2 also regulated the stemness phenotype in an ATG9B‐dependent manner, it was also verified in primary glioma stem cells." (PMID 35882624, 2022). "In comparison to low-grade glioma, GBM cells showed higher ATG9B expression, and enhanced knocking down of ATG9B, which in turn decreased autophagy and resistance to TMZ." (PMID 38398197, 2024). "The correlation between ATG9B and PROM1 expression was also consistent with coimmunostaining of frozen glioma sections." (PMID 35882624, 2022).
glioma (continued). "Our study unveiled that ASCL2 improved basal autophagy to maintain stemness through transcriptional regulation of ATG9B and that elevated ASCL2 promoted glioma progression in vivo." (PMID 35882624, 2022). "As the function and mechanism of the ASCL2‐ATG9B axis was revealed in gliomas, we further considered the relationship between ASCL2 and ATG9B in glioma samples." (PMID 35882624, 2022). "We further proved that ASCL2 was positively correlated with ATG9B and that the ASCL2‐ATG9B axis could be an independent prognostic factor, which indicated that the ASCL2‐ATG9B axis might be a functional unit in regulating glioma progression." (PMID 35882624, 2022). "Furthermore, when we treated two different mIDH1 mouse glioma cell models with α-ketoglutarate (α-KG), we found that the mIDH1 cells reverted the expression patterns showing significant reduction in several key autophagy regulators including pATG4b, UVRAG, ATG7, and ATG9b." (PMID 40964044, 2025). "Cell viability was assessed in both human (SJ-GBM2 mIDH1) and murine glioma (mIDH1 NPAI, mIDH1 CPAI, and mIDH1 RPAI) cells treated with ATG9b siRNAs, both in the presence and absence of IR." (PMID 40964044, 2025).
hepatocellular carcinoma (4 papers, 2019 to 2021). A malignant tumor that arises from hepatocytes. "For instance, Atg9b has been linked to various pathologies, including hepatocellular carcinoma (HCC), and a combination of suppressed Atg9b expression and decreased autophagy correlates with poor prognosis for patients with HCC (Wang, Tan, Li, & Feng, 2017)." (PMID 32627317, 2020).
breast tumors (3 papers, 2020 to 2026). "On the contrary to our findings, in a previous study on breast tumors, promoter hypermethylation of ATG9A, ATG9B, ATG2B, and ATG4D genes was linked to reduced gene expression." (PMID 40949798, 2025). "ATG9B has lower expression level in invasive breast tumors than matched normal tissues." (PMID 33194339, 2020).
liver cancer (3 papers, 2021 to 2025). An epithelial or non-epithelial malignant neoplasm that arises from the liver. "The ARNTL expression was down-regulated in the liver cancer tissues and liver cancer cells transfected with ATG9B-4." (PMID 40258750, 2025). "The results of OD value indicated that CDK5 knockdown effectively suppressed the proliferation of liver cancer cells induced by ATG9B-4." (PMID 40258750, 2025). "However, studies have reported that the expression level of ATG9B is involved in tumorigenesis in colon, breast, and liver cancers." (PMID 38706859, 2024).
gastric cancer (2 papers, 2016 to 2023). A primary or metastatic malignant neoplasm involving the stomach. "It has been reported that ATG2B, ATG5, ATG9B, ATG12, and ATG16L1 are closely related to gastric cancer (GC)." (PMID 37629426, 2023).
melanoma (2 papers, 2021 to 2023). A malignant, usually aggressive tumor composed of atypical, neoplastic melanocytes. "We obtained the risk scores of patients with melanoma: risk score = (−0.379123977 × expression of IFNG) + (−0.662084468 × expression of DAPK2) + (0.342818269 × expression of ATG9B) + (0.406559238 × expression of PTK6) + (0.807218069 × expression of BIRC5) + (0.364523721 × expression of EGFR)." (PMID 36690663, 2023). "The results confirmed that APOL1 have higher expression in GSE46517 while ATG16L2, DAPK2, ATG9B and EGFR have lower expression in GSE15605 for primary melanoma compared with normal skin." (PMID 34809598, 2021). "Melanoma patients with high expression of BIRC5, EGFR, and ATG9B had a worse prognosis." (PMID 36690663, 2023).
neuroblastoma (2 papers, 2014 to 2017). Neuroblastoma (NB) is the most common solid, extracranial childhood tumor. "Atg4B, Atg7 and Atg9B were not detectable in CSF; however, the antibodies used detected these proteins in human SH-SY5Y neuroblastoma cell lysates (data not shown)." (PMID 24101586, 2014).
Pancreatic cancer (2 papers, 2016). "A markedly high number of copy number deletions were also observed for the PIK3C3 gene in Pancreatic cancer (24%), whereas copy number amplifications for ATG9B (17%), ATG4B (16%) and MAP1LC3C (13%) were commonly found." (PMID 27256984, 2016).
coronary artery disease (1 paper, 2019). "The present study aimed to investigate the effects of ATG9B rs2373929 and rs7830 gene polymorphisms on the predisposition to coronary artery disease (CAD)." (PMID 31384404, 2019).
glioblastoma multiforme (1 paper, 2022). "In glioblastoma multiforme (GBM), DAB2IP negatively regulated ATG9B expression and inhibited tumour autophagy by blocking the Wnt/β‐catenin pathway." (PMID 36536485, 2022).
liver fibrosis (1 paper, 2024). "Our observations also revealed the role and underlying mechanisms of ATG9b in regulating ACD of activated HSCs to alleviate liver fibrosis." (PMID 37970991, 2024). "This study provides evidence for ATG9b as a new target gene and propranolol as an agent to alleviate liver fibrosis by regulating ACD of activated HSCs." (PMID 37970991, 2024). "This study also elucidated the important role of ATG9b in liver fibrosis." (PMID 37970991, 2024). "We also explored the role of propranolol and ATG9b in liver fibrosis in vivo." (PMID 37970991, 2024). "Upregulation of ATG9b attenuated the activation of HSCs and improved CCl4‐induced liver fibrosis." (PMID 37970991, 2024). "Propranolol induces ACD of activated HSCs to improve liver fibrosis in an ATG9b‐dependent manner." (PMID 37970991, 2024). "This is the first study to reveal the role of ATG9b in liver fibrosis." (PMID 37970991, 2024). "In addition, ATG9b overexpression protected mice from CCl4‐induced liver fibrosis." (PMID 37970991, 2024). "Whether ATG9b influences hepatocytes in liver fibrosis has yet to be studied." (PMID 37970991, 2024). "Our findings also suggest the use of propranolol as a potential agent and ATG9b as a regulated gene for HSC ACD, which promotes the development of treatment against liver fibrosis." (PMID 37970991, 2024). "ATG9b upregulation promoted ACD of HSCs and alleviated liver fibrosis in vivo." (PMID 37970991, 2024). "Another limitation of this study is that ATG9b has not been studied in liver fibrosis in the clinics." (PMID 37970991, 2024). "This study aimed to identify the effect of ATG9b on HSC death and liver fibrosis." (PMID 37970991, 2024). "The role of autophagy‐related protein 9b (ATG9b) in the ACD of HSC and liver fibrosis has not been revealed before." (PMID 37970991, 2024).
lung adenocarcinoma (1 paper, 2021). A carcinoma that arises from the lung and is characterized by the presence of malignant glandular epithelial cells. "For instance, Wang and colleagues recently reported a five-autophagy-related signature (ITGB4, NLRC4, ATG9B, CDKN2A, ERO1A) based on overall survival in patients with lung adenocarcinoma." (PMID 34252349, 2021).
pulmonary fibrosis (1 paper, 2023). Chronic progressive interstitial lung disorder characterized by the replacement of the lung tissue by connective tissue, leading to progressive dyspnea, respiratory failure, or right heart failure. "It has been shown that bleomycin induces an increase in autophagic activity and upregulation of autophagy-related gene ATG9B expression during pulmonary fibrosis, which is involved in the development of pulmonary fibrosis." (PMID 37616056, 2023).